SPDYE2 (speedy/RINGO cell cycle regulator family member E2)
Synonyms: MGC119295; SPDYB2-L1; SPDYB2L1
Tractability: No criterion of Open Targets' tractability assessment is met for any kind of drug.
Gene: Protein-coding gene on chromosome 7 (102,551,226 to 102,563,538, forward strand). Ensembl gene ENSG00000205238.
Gene Ontology:
Molecular function: protein binding; protein kinase binding
Genetic constraint (gnomAD): Loss-of-function variants: 0 observed, 3.54 expected, observed/expected ratio (o/e) 0, 90% interval 0 to 0.84. That is too few expected variants to judge how well the gene tolerates losing a copy. Missense variants: 0 observed, 40.84 expected, observed/expected ratio (o/e) 0, 90% interval 0 to 0.073. Synonymous variants: 0 observed, 13.69 expected, observed/expected ratio (o/e) 0, 90% interval 0 to 0.22.
Homologues: Orthologues: chimpanzee SPDYE6 (88% identical), mouse Spdye4a (33% identical), rat Spdye4 (33% identical), mouse Spdye4b (29% identical). Paralogues in human: SPDYE2B (99% identical), SPDYE6 (99% identical), SPDYE5 (96% identical), SPDYE21 (95% identical), SPDYE1 (89% identical), SPDYE18 (82% identical), SPDYE16 (82% identical), SPDYE3 (62% identical), SPDYE12 (55% identical), SPDYE13 (55% identical), SPDYE14 (55% identical), SPDYE15 (55% identical), and 6 more.